BRCA2 (BRCA2 DNA repair associated)
Diseases named in the same sentence as BRCA2 in open-access papers (continued):
Sharing a sentence is not in itself a finding about the gene and the disease.
breast cancer (continued). "On the other hand, our inclusion of 10 BRCA2 mutations detected only through a survey of male breast cancers obviously introduces a bias in the opposite direction." (PMID 12698193, 2003). "Several early studies of alterations at the FHIT locus in breast cancer reported reduced expression of Fhit in ∼40–60% of mammary carcinomas and an elevated frequency of loss in BRCA2-linked breast carcinomas." (PMID 12771912, 2003). "This was a case–control study comparing tamoxifen history in bilateral breast cancer patients with a BRCA1 or BRCA2 mutation with that in unilateral patients, also with a mutation." (PMID 11870509, 2002). "Such a model needs to incorporate both the effects of both the known susceptibility genes (BRCA1 and BRCA2) and of other possible breast cancer susceptibility genes." (PMID 11857015, 2002). "For example, truncating mutations in BRCA1 and BRCA2 confer a high risk of breast cancer, but rarely have somatic mutations in sporadic tumours been reported in either gene." (PMID 12177782, 2002). "Selection of breast cancer patients with a mutation in BRCA1 or BRCA2 genes revealed a significantly higher mean value compared to the normal population only for the LDR MN assay." (PMID 12454765, 2002). "A practical implication of these different age-incidence patterns, is that BRCA1 mutation carriers are more likely to develop breast cancer at a younger age than BRCA2 mutation carriers." (PMID 11857015, 2002). "The cumulative breast cancer risk for a BRCA2 mutation carrier was estimated to be 68.7% and the corresponding ovarian cancer risk was 16.6%." (PMID 11857015, 2002). "The average breast cancer cumulative risk by age 70 years in BRCA2 mutation carriers is 50.26% (7.2 and 99.3% at the 10 and 90% percentiles respectively)." (PMID 11857015, 2002). "The cumulative risk of breast cancer for BRCA2 mutation carriers was estimated to be 50.3% by age 70 years." (PMID 11857015, 2002). "In contrast, the estimated breast cancer relative risk for BRCA2 mutation carriers as compared to population incidence was 17.52 for the age group 30–39 years but virtually constant over age 40 years at around 11–12 (Ptrend=0.697)." (PMID 11857015, 2002). "Mutations of the BRCA1 or BRCA2 genes have been shown to strongly predispose towards the development of contralateral breast cancer in patients from large multi-case families." (PMID 11556836, 2001). "The total proportion of mutations was low (25%), although the percentage of mutations in the BRCA1 and BRCA2 genes was higher, considering the breast and ovarian cancer families and the male breast cancer families respectively." (PMID 10755399, 2000). "Mutations in the genes BRCA1 and BRCA2 are rare in the population and account for a small fraction of all breast cancer in the UK." (PMID 11044354, 2000). "Our series were composed of 16 cases of breast carcinoma in women with a germline Brca1 gene mutation, and of four cases with Brca2 mutation." (PMID 11044356, 2000). "Within the group of small breast-cancer-only families, a bilateral breast cancer case or a unilateral breast cancer case diagnosed before age 40 independently predicted finding a BRCA1 or BRCA2 mutation (P = 0.005 and P = 0.02, respectively)." (PMID 10188893, 1999). "We screened the 185delAG and 5382insC (BRCA1) and the 6174delT (BRCA2) mutation in 298 Spanish women with breast cancer." (PMID 10098775, 1999). "Mutations in the BRCA1/BRCA2 genes account for varying proportions of breast cancer families studied, and demonstrate considerable variation in mutational spectra coincident with ethnic and geographical diversity." (PMID 9836472, 1998). "A total of 28 male breast cancer patients were tested for BRCA2 mutations; two frameshifts and one putative missense mutation were identified." (PMID 9400938, 1997).
breast cancer (continued). "Germline mutations of the BRCA2 gene on chromosome 13q12-q13 predispose to the development of early-onset breast cancer and ovarian cancer." (PMID 9365162, 1997). "Individuals who inherit the BRCA1 mutations confront a lifetime breast cancer risk of 65%–80% and an ovarian cancer risk of 37%–62%, whereas BRCA2 mutation carriers face a 45%–85% chance of breast cancer and a 11%–23% chance of ovarian cancer over their lifetimes." (PMID 40904409, 2025). "According to a meta-analysis of 6 high-risk screening trials, one-third of breast cancers in BRCA2 carriers under 40 (6/18, 33.3%) could only be detected using mammography alone, including two DCISs." (PMID 41083355, 2025). "Notably, while BRCA1 and BRCA2 mutations are predominantly associated with breast cancer, this study detected BRCA2 protein in the lung cancer model, suggesting a potential, although lower, role of this protein in lung cancer." (PMID 40584122, 2025). "Additionally, none of the studies included in this review reported BRCA1 or BRCA2 gene expression or genetic screening for breast cancer risk." (PMID 40427149, 2025). "In addition, the frequency of pathological genetic mutations in BRCA1 and BRCA2 in sporadic breast cancers in the South Korean population was found to be 3.1%." (PMID 40361383, 2025). "Additionally, the presence of a BRCA1 or BRCA2 mutation, which indicates a high risk of developing breast cancer, has been linked to greater psychological distress and diminished quality of life, even in the absence of an active cancer diagnosis." (PMID 41192943, 2025). "Testing for BRCA1 and BRCA2 mutations has become standard practice for females with breast cancer in their families, but other genetic abnormalities or variations may also be relevant in therapeutic settings." (PMID 40735254, 2025). "A deeper understanding of how SNPs affect BRCA2 regulation and expression is essential for advancing breast cancer research and may offer valuable diagnostic and prognostic insights." (PMID 40843725, 2025). "However, it is estimated that only about 10–15% of male breast cancer cases are associated with BRCA2 mutations, indicating that the majority of these tumors occur without this genetic alteration." (PMID 40243654, 2025). "Moreover, through a MetaCore functional enrichment analysis, GNPDA1 and SLC25A16 were associated with the BRCA1, BRCA2, and pro-oncogenic actions of the androgen receptor in breast cancer." (PMID 40278313, 2025). "For instance, the missense pathogenic variant c.7271T>G in ATM may considerably increase the risk of breast cancer in a similar proportion as P/LP variants in BRCA2." (PMID 39858629, 2025). "Indeed, patients carrying BRCA1 mutations have a lifetime risk of breast cancer of 40%–87%, while the risk in those with BRCA2 mutations is 25%–30%." (PMID 40338860, 2025). "For example, previvors with a P/LP in the BRCA1 gene have up to a 72 % lifetime breast cancer risk and up to a 44 % lifetime ovarian cancer risk; however, previvors with a P/LP in the BRCA2 gene have up to a 69 % lifetime breast cancer risk and a 17 % lifetime ovarian cancer risk." (PMID 40485758, 2025). "Future studies should investigate the contribution of germline mutations of BRCA1 and BRCA2 genes in a larger case-control cohort study of Brunei breast cancer population to confirm and further investigate the contribution of these germline mutations to breast cancer risk." (PMID 40531958, 2025).
breast cancer (continued). "A main concern about the surgical treatment of BRCA1/BRCA2 mutations breast cancers is whether breast conserving surgery (BCS) combined with radiotherapy is equivalent to radical mastectomy or not." (PMID 41303129, 2025). "The main outcome was prevalence of P/LP variants in BRCA1 and BRCA2 in women with breast cancer." (PMID 40952741, 2025). "For BRCA1 and BRCA2 carriers, few studies with small sample sizes, high heterogeneity, low quality, and varied measurements of exposure have assessed the impact of modifiable risk factors on breast cancer risk." (PMID 39858629, 2025). "This trend may be partially explained by the fact that BL reconstructions are often chosen by patients with genetic or familial risk factors, such as BRCA1 or BRCA2 mutations, which are linked to an earlier onset of breast cancer." (PMID 40004590, 2025). "BRCA1 and BRCA2 mutations contribute to approximately 10–15% of all breast cancers." (PMID 40941615, 2025). "The lifetime risk for breast cancer with a pathogenic variant of BRCA2 is about 45–65%." (PMID 39621070, 2025). "Besides BRCA1 and BRCA2 mutations that markedly increase breast cancer risk, hundreds of low- and moderate-risk susceptibility variants have been identified, including caspase-8 (rs2293554, rs6723097,), TIMP-2 (rs7501477), and FSCN1 (rs56156320, rs3801004,)." (PMID 39614126, 2025). "The principle of synthetic lethality, which refers to the loss of viability resulting from the disruption of two genes, which, individually, do not cause lethality This principle is primarily used to treat advanced ovarian and breast cancers associated with BRCA1 or BRCA2 gene mutations." (PMID 40978031, 2025). "In addition, the analyses reported reduced breast cancer-specific mortality in breast cancer-affected women carrying BRCA1/BRCA2 P/LP variants combined (RR 0.26; 95% CI 0.18–0.39)." (PMID 39858629, 2025). "For the two patients identified with these mutations, there is a 50% chance that their affected family members carried the same BRCA2 mutation that could lead to the development of breast cancer." (PMID 40531958, 2025). "Women who carry BRCA1 and/or BRCA2 pathogenic variants develop breast cancer at a mean age of 45." (PMID 40862808, 2025). "BRCA2 mutation carriers have a markedly elevated relative risk (up to 44-fold), and approximately 10% may develop breast cancer during their lifetime." (PMID 41510417, 2025). "In addition, a family history of ovarian cancer, particularly in cases involving BRCA1 or BRCA2 mutations, is also a recognized risk factor for breast cancer." (PMID 40800071, 2025). "His daughter had a history of breast cancer, and he had a BRCA2 pathogenic variant." (PMID 39980666, 2025). "Typically, BRCA2-associated breast cancers are usually hormone receptor positive." (PMID 39392573, 2025). "BRCA2 and Klinefelter’s syndrome were associated with an increased risk of male breast cancer." (PMID 40160874, 2025). "For example, BRCA1 and BRCA2 mutations predispose both men and women to breast cancer." (PMID 41589155, 2025). "Notably, there were only three statistically significant results, though all three were associations between BRCA2 variants and breast cancer." (PMID 39799398, 2025). "Consequently, germline (g)BRCA1 and BRCA2 mutations are associated with a lifetime risk of breast cancer of up to 72%." (PMID 39392573, 2025).
breast cancer (continued). "Additionally, a subsequent investigation in the Russian population, specifically in the Voronezh region, identified a notable correlation between the rs4987117 variant of the BRCA2 gene and the risk of hereditary breast cancer." (PMID 40843725, 2025). "BRCA2 mutations significantly increase the risk of both prostate and breast cancer in men." (PMID 41011057, 2025). "In men, BRCA2 mutations are more likely to predispose men to breast cancer, whereas in women, BRCA1 mutations may be comparable to BRCA2 mutations in predisposing women to breast cancer." (PMID 41589155, 2025). "Additionally, approximately 10% of women diagnosed with breast cancer before the age of 40 carry a BRCA1 or BRCA2 mutation." (PMID 41002733, 2025). "Interestingly, it can be inferred that cases with a late onset of OC and those with breast cancer are likely to have BRCA2 variants." (PMID 40323562, 2025). "To illustrate the new method, we selected the most significant 176 genes that could discriminate breast cancers with BRCA1 mutation from those with BRCA2 mutation, resulting in a 15×176 matrix." (PMID 41542084, 2025). "In BRCA2-deficient breast cancer, activated B cells and immature B cells are enriched." (PMID 40830526, 2025). "While BRCA1 and BRCA2 remain the most well-established genes linked to breast cancer risk, restricting testing to these two genes may overlook other clinically relevant mutations." (PMID 40800071, 2025). "(“fertility preservation” OR “oocyte cryopreservation” OR “embryo cryopreservation”) AND (“BRCA mutation” OR “BRCA1” OR “BRCA2”) AND (“hormone receptor status” OR “ER positive” OR “PR positive” OR “triple-negative breast cancer” OR “TNBC”) AND (“breast cancer”)." (PMID 41395617, 2025). "These genes are known to regulate important mechanisms concerning cell growth and DNA damage repair; thus, a mutation in BRCA1 and BRCA2 is often related to genomic instability, as cells continue to proliferate despite having DNA damage, which promotes breast cancer." (PMID 40227634, 2025). "Additionally, we identified BRCA2 variants in a family with two siblings (age 41 and 44 years) of multiple myeloma (MM) and five cases of breast cancer." (PMID 40047910, 2025). "In the case of BRCA2 mutation carriers, the cumulative risk of breast cancer is 31–56%." (PMID 40940924, 2025). "This case may serve as a valuable reference for diagnosing and treating breast cancer associated with BRCA2 exon 27 mutations." (PMID 40612353, 2025). "One person had a pathogenic variant of the BRCA2 gene (rs28897756) related to breast cancer." (PMID 40504832, 2025). "Somatic mutations in BRCA1 or BRCA2 were detected in 3 (6%) and 4 (8%) patients, respectively, and 59% of patients had hormone receptor-positive, human epidermal growth factor receptor 2-negative breast cancer." (PMID 39839709, 2025). "The tumor phenotype varies in breast cancer patients based on BRCA1 or BRCA2 germline mutations." (PMID 39997609, 2025). "Similarly, for BRCA2 mutation carriers, the cumulative risk of ovarian cancer by age 80 is 17% (95% CI, 11%-25%), and the cumulative risk of contralateral breast cancer 20 years after a breast cancer diagnosis is 26% (95% CI, 20%-33%)." (PMID 40065879, 2025). "About 5–10% of breast cancers are inherited with approximately 30% of the inherited breast cancers were attributed to germline mutations in high penetrance breast cancer susceptibility genes, Breast Cancer susceptibility genes type 1 (BRCA1) and Breast Cancer susceptibility gene type 2 (BRCA2)." (PMID 40531958, 2025). "Moreover, patients with BC and germline mutations in the breast cancer genes 1 or 2 (BRCA1/BRCA2), (gBRCAm), who are typically young women, often require more aggressive therapeutic interventions." (PMID 40805203, 2025). "In the breast cancer subgroup, variants in BRCA2 and BRCA1 were the most frequently detected." (PMID 39148954, 2024).
breast cancer (continued). "BRCA2 gene mutations are associated with an increased risk of male breast cancer, along with lesser-known gene mutations that could also increase this risk, such as mutations of the BRIP1 gene." (PMID 38912178, 2024). "The Gail model asks a series of questions, which include a medical history of breast cancer, a mutation in the BRCA1 or BRCA2 gene, age, age at first menstrual period, age at first live birth, first-degree relatives with breast cancer, breast biopsy, and race/ethnicity." (PMID 38501027, 2024). "In addition to known cancer variants, such as breast cancer-related BRCA1/BRCA2, our study highlights novel associations that should be considered in cancer susceptibility screenings." (PMID 39132489, 2024). "Thus, homologous recombination repair is defective in breast cancers with germline P/LP BRCA1 or BRCA2 variants." (PMID 39507757, 2024). "Next, we determined whether MLH1 loss can suppress growth of BRCA2-deficient mouse mammary tumor cells (KB2P1.21)." (PMID 38271119, 2024). "BRCA2’s role in cancer well-established, as elevated BRCA2 expression is associated with a significantly reduced number of stromal cells and high infiltration of both beneficial and detrimental immune cells in breast cancer." (PMID 39267750, 2024). "Approximately 75% of breast cancer patients have mutations or low expression of BRCA1 or BRCA2." (PMID 38244591, 2024). "Moreover, the genetic landscape of OC is explored through the examination of mutations in genes such as BRCA1 and BRCA2 (Breast Cancer genes 1 and 2)." (PMID 38535506, 2024). "Furthermore, mutations in BRCA1 and BRCA2 are more commonly associated with HER2-positive breast cancer." (PMID 38256428, 2024). "Additionally, the patient’s son discovered a novel BRCA2 mutation, and his daughter developed breast cancer." (PMID 39364320, 2024). "Furthermore, we show that estrogen receptor α (ERα) induces MLH1 expression, which explains why BRCA2-associated tumors are mostly ER positive, which is a major subtype of breast cancer cases." (PMID 38271119, 2024). "We may thus have a smaller fraction of individuals at the end-tail of the PRS distribution (PRS >99th percentile tested in this study) with an odds ratio equivalent to BRCA1 (OR = 10.57) and BRCA2 (OR = 5.85) mutations in the field of breast cancer." (PMID 38970920, 2024). "There are 1508 BRCA1 and BRCA2 mutation carriers, 12,265 breast cancers (8755 diagnosed before age 45) at enrolment with age‐matched population‐ and family‐based controls, 2250 incident breast cancers including 1135 in those unaffected at baseline." (PMID 38504141, 2024). "While the retrospective studies have suggested that the cancer risk might vary between BRCA1 and BRCA2 mutation carriers, recent prospective studies have shown that the lifetime breast cancer risk is similar for both genes ranging from 55 to 72%." (PMID 38254240, 2024). "Similarly, the immunogenicity and the response to immunotherapy of breast cancers seem to be different between tumors with a BRCA1 or a BRCA2 mutation." (PMID 39544936, 2024). "It is reported that 55–72% of women who inherit a harmful BRCA1 variant and 45–69% of women who inherit a harmful BRCA2 mutation will develop breast cancer by 70–80 years of age, while the chances of developing breast cancer among the general population at some point in their lives is about 13%." (PMID 38672725, 2024). "A subsequent genetic analysis found a breast cancer 2 (BRCA2) gene mutation." (PMID 38524061, 2024). "Notably, while BRCA1/2 germline variants accounted for 46% (23% in BRCA1 and 23% in BRCA2) of these pathogenic changes, a substantial 54% were found in other breast cancer predisposition genes." (PMID 39590369, 2024). "Furthermore, a germline mutation in the BRCA1 gene is associated with a higher lifetime risk (72%) for developing breast cancer than for BRCA2 mutation carriers (69%)." (PMID 39011181, 2024).